TMEM97 (transmembrane protein 97)
Diseases named in the same sentence as TMEM97 in open-access papers (continued):
Sharing a sentence is not in itself a finding about the gene and the disease.
Anxiety (4 papers, 2020 to 2025). Intense feelings of nervousness, tension, or panic often arise in response to interpersonal stresses. "To test the behavioral consequence of s2R/TMEM97 loss in modulating affective behaviors in the naive state, we evaluated anxiety-like and depressive-like behaviors using an affective behavior battery in WT and Tmem97 KO mice." (PMID 38866499, 2024). "We found that WT female mice have an elevated Z score that is associated with high anxiety-like behavior compared with WT males, Tmem97 KO males, and Tmem97 KO female mice." (PMID 38866499, 2024). "Taken together, the loss of Tmem97 expression is associated with reduced anxiety-like and depressive-like behaviors in LDP and TST, respectively." (PMID 38866499, 2024). "In this study, the loss of Tmem97 expression was found to be associated with reduced anxiety-like and depressive-like behaviors at baseline in the LDP and TST but not in other affective behaviors." (PMID 38866499, 2024). "We next investigated the extent to which Tmem97 is associated with the development of anxiety-like and depressive-like behaviors induced by prolonged neuropathic injury." (PMID 38866499, 2024). "Post hoc analysis of the “emotionality” Z score by sex shows a similar trend of reduced anxiety- and depressive-like behaviors associated with the loss of Tmem97 in both females (p = 0.0568) and males (p = 0.0889)." (PMID 38866499, 2024). "The study revealed that the loss of Tmem97 expression was linked to reduced anxiety-like and depressive-like behaviors in specific assays largely in female mice only." (PMID 38866499, 2024). "We stratified the postoperative behavioral changes by sex to investigate the potential sexual dimorphism underlying Tmem97-associated anxiety-like or depressive-like behaviors." (PMID 38866499, 2024). "Thus, the loss of Tmem97 associated with less anxiety-like behaviors appears to be driven by WT female mice in LDP." (PMID 38866499, 2024). "Our study focused primarily on the gene, Tmem97, to characterize its effect in various affective behaviors and to what extent it changes postoperative anxiety-like and depressive-like behaviors after exposing to prolonged neuropathic injury." (PMID 38866499, 2024). "The effect of genotype on anxiety-like and depressive-like behaviors was also influenced by sex, with female Tmem97 KO mice showing unique patterns of reduced anxiety-like and depressive-like behavior in LDP and TST, respectively." (PMID 38866499, 2024). "In LDP, we found that female Tmem97 KO mice show a trend of reduced anxiety-like behaviors in certain parameters compared with female WT mice." (PMID 38866499, 2024). "In the current study, we assessed the role of s2R/TMEM97 in modulating neuropathic injury-induced anxiety-like and depressive-like behaviors using wild-type and global Tmem97 knock-out mice." (PMID 38866499, 2024). "Overall, based on the literature, the modulation of s2R/TMEM97 found in the brain plays important role in many diseases and is associated with reduced anxiety-like and depressive-like behaviors in mice." (PMID 38866499, 2024). "Our results demonstrate that female Tmem97 KO mice show less anxiety-like and depressive-like behaviors in light/dark preference and tail suspension tests but not in an open field, elevated plus maze, and forced swim tests at baseline." (PMID 38866499, 2024). "Our results also point to a broader question of whether having Tmem97-regulated heightened anxiety-/depressive-like traits is evolutionarily advantageous for individual fitness." (PMID 38866499, 2024). "The results of the two types of behavioral batteries together suggest that Tmem97-associated modulatory role is specific to anxiety-like and depressive-like behaviors and there is no overt executive function-related behavioral confounding this interpretation." (PMID 38866499, 2024). "Tmem97 may regulate anxiety-like and depressive-like behavior in a modality-dependent manner." (PMID 38866499, 2024).
Anxiety (continued). "Our findings indicated that Tmem97 KO female mice show reduced anxiety-like behaviors in LDP and TST but not in OF, EPM, EZM, and FST." (PMID 38866499, 2024).
Huntington disease (4 papers, 2022 to 2025). Huntington disease (HD) is a rare neurodegenerative disorder of the central nervous system characterized by unwanted choreatic movements, behavioral and psychiatric disturbances and dementia. "Pharmacological targeting of σ2R/TMEM97 has neuroprotective effects in a number of models of neurodegenerative conditions, including traumatic brain injury, Huntington's disease, and retinal ganglion cell degeneration." (PMID 38117854, 2023).
meningioma (4 papers, 2007 to 2025). A generally slow growing tumor attached to the dura mater. "TMEM97 was first identified as a downregulated gene in meningioma and was later found to be transcriptional target of the BRCA1 gene." (PMID 18070364, 2007). "Meningioma-associated protein (MAC30), also named (TMEM97) transmembrane protein 97, a member of the insulin-like growth factor-binding protein family, was firstly designated as tumor suppressor gene in view of its upregulation in meningiomas." (PMID 32904598, 2020). "Interestingly, σ2R/TMEM97 was found to be downregulated in other cancers, such as meningiomas, pancreatic, and renal cancers, suggesting that it may have a complex and cancer-cell-type-dependent role in cancer development." (PMID 41008535, 2025).
Parkinson disease (4 papers, 2022 to 2025). A progressive degenerative disorder of the central nervous system characterized by loss of dopamine producing neurons in the substantia nigra and the presence of Lewy bodies in the substantia nigra and locus coeruleus. "In a model of Parkinson’s disease, a small-molecule modulator of σ2R/TMEM97 effectively reduces α-synuclein oligomer toxicity through regulating intracellular lipid vesicle trafficking, autophagy, and cholesterol metabolism." (PMID 41008535, 2025).
renal carcinoma (4 papers, 2018 to 2025). A carcinoma arising from the epithelium of the renal parenchyma or the renal pelvis. "According to the GESA bioinformatics results, we predicted that TMEM97 was positively associated with the PI3K‐AKT‐mTOR signalling pathway in renal cancer." (PMID 34783163, 2021). "The GSEA results suggested that TMEM97 is positively correlated with the PI3K‐AKT‐mTOR signalling pathway in renal cancer." (PMID 34783163, 2021). "Third, we predicted probable signalling pathway correlations with TMEM97 in renal cancer by studying bioinformatics analysis." (PMID 34783163, 2021). "We speculated that TMEM97 might act as a tumour suppressor during the development of renal cancer, and PB28 had a therapeutic effect on it." (PMID 34783163, 2021). "To this end, we investigated the mechanism of TMEM97 in renal cancer." (PMID 34783163, 2021). "Herein, we assessed the efficacy of PB28 and sigma‐2 receptor antagonist 1 and a probable and unknown mechanism by which the sigma‐2 receptor/TMEM97 affects renal cancer." (PMID 34783163, 2021). "Indeed, the expression of TMEM97 is increased in several types of cancer as described later in this review, except in pancreatic and renal cancers that both display a low expression level of TMEM97 protein and mRNA." (PMID 30574087, 2018). "Therefore, we hypothesized that TMEM97 plays a vital role in the development of renal cancer, PB28 might serve as a new therapeutical agent for renal cancer treatment." (PMID 34783163, 2021). "As multidrug resistance is common in human renal cancer, the effects of PB28 and cisplatin on renal cancer cells were investigated to study the potential implication of TMEM97 in drug sensitivity and in vitro chemoresistance." (PMID 34783163, 2021). "In conclusion, PB28 binding to TMEM97 might inhibit phosphorylation of constituents of the PI3K‐AKT‐mTOR signalling pathway, resulting in decreased proliferation, migration and invasion of renal cancer in vitro and in vivo." (PMID 34783163, 2021).
cognitive deficits (3 papers, 2020 to 2024). "In an animal model with Alzheimer’s-like plaque deposition, TMEM97 (Sigma-2) modulators improved cognitive deficits." (PMID 38319380, 2024). "Further, the activation of the sigma-2 receptor is neuroprotective: a novel sigma-2 receptor/TMEM97 modulator, DKR-1677, protects neurons from death and cognitive impairment after blast-mediated traumatic brain injury (TBI)." (PMID 33233619, 2020).
non-small cell lung carcinoma (3 papers, 2019 to 2021). A group of at least three distinct histological types of lung cancer, including non-small cell squamous cell carcinoma, adenocarcinoma, and large cell carcinoma. "Elevated TMEM97 expression has been associated with poor clinical outcomes and tumor progression in gastric, colorectal, breast and ovarian, squamous cell lung cancer (SQCLC), and non-small cell lung cancer (NSCLC)." (PMID 31695608, 2019).
retinal diseases (3 papers, 2023 to 2025). "Our study, identifying TMEM97 as a novel regulator of RPE-cell pEMT, bridges these gaps, opening new opportunities for potential interventions to mitigate RPE dysfunction in retinal diseases." (PMID 39995975, 2025).
hepatocellular carcinoma (2 papers, 2022 to 2026). A malignant tumor that arises from hepatocytes. "TMEM97 (MAC30) is highly expressed in breast and hepatocellular carcinomas." (PMID 36254814, 2022).
neuroblastoma (2 papers, 2019 to 2020). Neuroblastoma (NB) is the most common solid, extracranial childhood tumor. "A possible regulatory role of σ2R/TMEM97 in the intracellular Ca2+ homeostasis has already been suggested in the human neuroblastoma cells, SK-N-SH cell line, using high concentrations of ligands BD737 and CB-64D." (PMID 31973006, 2020).
Obesity (2 papers, 2019 to 2024). Accumulation of substantial excess body fat. "Interestingly, the sigma-2 receptor (TMEM97) is involved in cholesterol homeostasis; therefore, studies showing what changes may occur in obese organisms or those at risk of developing obesity and treated with ligands of this receptor are important." (PMID 39065709, 2024). "Several of these cis-eQTLs influence the mRNA levels of genes with important roles in meat (CTSF) and carcass quality (TAPT1), lipid metabolism (TMEM97) and obesity (MARC2), thus evidencing the practical importance of dissecting the genetic mechanisms involved in their expression." (PMID 31234802, 2019).
triple-negative breast carcinoma (2 papers, 2020 to 2025). An invasive breast carcinoma which is negative for expression of estrogen receptor (ER), progesterone receptor (PR), and human epidermal growth factor receptor 2 (HER2). "On the other hand, the role of σ2R/TMEM97 on Ca2+ homeostasis in triple negative breast cancer cells remains largely unexplored." (PMID 31973006, 2020). "Here, we confirmed the enhanced σ2R/TMEM97 expression in the triple negative breast cancer cell line MDA-MB-231 cells by different experimental approaches." (PMID 31973006, 2020). "In the present study, we examined the antiproliferative effect of NO1 in the triple negative breast cancer cell lines, MDA-MB-231 and MDA-MB-468 cells, and the downstream mechanisms of σ2R/TMEM97." (PMID 31973006, 2020). "The novel σ2R/TMEM97 fluorescent ligand, NO1, reduced the proliferation and survival of the triple negative breast cancer cell lines (TNBC: MDA-MB-231 and MDA-MB-468 cell lines), due to NO1-induced apoptosis." (PMID 31973006, 2020). "The inhibition of σ2R/TMEM97 in both TNBC leads to the induction of apoptosis and the reduction of cell proliferation, thus supporting the relevance of this protein in the physiology of triple negative breast cancer cells." (PMID 31973006, 2020).
adenomyosis (1 paper, 2022). The growth of endometrial tissue inside the muscular wall of the uterine corpus. "The microarray dataset analysis revealed that the expression levels of TMEM97, GLT8D2, NME5, STEAP1, and TOMM20 were significantly downregulated in the endometrium of women with adenomyosis compared with those in the control group (p < 0.05)." (PMID 36685847, 2022). "The expression of TMEM97 was downregulated in the adenomyosis group, but without statistical significance." (PMID 36685847, 2022).
alcohol use disorder (1 paper, 2019). "A new study has also shown that Sigma-2 receptor/TMEM97 is involved in alcohol withdrawal behaviors, indicating that this receptor can be targeted to treat alcohol use disorder." (PMID 31178723, 2019).
bladder cancer (1 paper, 2020). "The data suggest that TMEM97 expression is differentially regulated by EGF in different bladder cancer cell lines." (PMID 32668577, 2020).
cervix adenocarcinoma (1 paper, 2019). "We used cervix adenocarcinoma HeLa as reference sample, because of its high expression of both S1R and TMEM97/S2R." (PMID 31156430, 2019).
corneal diseases (1 paper, 2025). "Targeting the σ2R/TMEM97 pathway may therefore provide an alternative approach for enhancing corneal wound healing and treating corneal diseases such as diabetic corneal neuropathy." (PMID 41008535, 2025).
injury (1 paper, 2024). Damage inflicted on the body as the direct or indirect result of an external force, with or without disruption of structural continuity. "WT mice, but not Tmem97 KO mice, developed a prolonged neuropathic pain-induced depressive-like phenotype when tested 10 weeks after nerve injury in females." (PMID 38866499, 2024).
ischemia (1 paper, 2022). A hypoperfusion of the BLOOD through an organ or tissue caused by a PATHOLOGIC CONSTRICTION or obstruction of its BLOOD VESSELS, or an absence of BLOOD CIRCULATION. "Moreover, intravitreal injection of a selective, high-affinity σ2R/TMEM97 ligand DKR-1677 protects RGCs from ischemia damage in wildtype (TMEM97+/+) mice." (PMID 36456686, 2022).
lysosomal storage disorder (1 paper, 2018). "TMEM97 is thought to be involved in cholesterol trafficking through its association with lysosomal cholesterol transporter NPC1, a protein whose loss results in a fatal lysosomal storage disorder, Niemann–Pick disease type C119." (PMID 30443021, 2018).
metastatic colorectal cancer (1 paper, 2010). "Interestingly, TMEM97 was survival significant in both cohorts, and it was shown previously to play a role in primary and metastatic colorectal cancers." (PMID 20158880, 2010).
Niemann-Pick disease (1 paper, 2021). A group of inherited, severe metabolic disorders in which sphingomyelin accumulates in lysosomes in cells. "More recently, it was reported that S2R (TMEM97) knockdown attenuated Niemann–Pick disease phenotypes in a mouse model, linking S2R to lysosomal cholesterol export." (PMID 33234676, 2021).
retinal ischemia (1 paper, 2022). A ischemic disease that involves the retina. "When challenged by retinal ischemia, the RGCs in TMEM97−/− mice had significantly higher survival rates than the RGCs having fully functional σ2R/TMEM97 in wildtype mice." (PMID 36456686, 2022). "Retinal ischemia also induced an increase in PERG latency in the retina of the wildtype mouse, but not in the retina of the TMEM97−/− mouse." (PMID 36456686, 2022).
skin cutaneous melanoma (1 paper, 2023). "Moreover, high levels of TMEM97 expression are associated with patients with poor overall survival probability, hinting that it may be used as a prognostic marker of survival in patients affected by skin cutaneous melanoma (SKCM)." (PMID 37298633, 2023).
systemic sclerosis (1 paper, 2023). A chronic disorder, possibly autoimmune, marked by excessive production of collagen which results in hardening and thickening of body tissues. "Both TMEM97 and PGRMC1 were regulated at the transcript level in skin cells by the topically applied Wnt/beta-catenin inhibitor C-82 under investigation in a clinical trial in individuals with systemic sclerosis, suggesting that Wnt signaling regulates TMEM97." (PMID 37047224, 2023).
cancer (73 papers, 2007 to 2025). A tumor composed of atypical neoplastic, often pleomorphic cells that invade other tissues. "Primarily studied in cancers, TMEM97 is also linked to cholesterol homeostasis, Niemann-Pick disease, Alzheimer disease, and neuropathic pain." (PMID 39995975, 2025). "TMEM97 has a cell proliferative effect on cancer development and has been associated with dysplasia and cancer pathways." (PMID 41462954, 2025). "TMEM97 is a drug-binding site implicated in major diseases such as cancer, yet its molecular functions remain obscure." (PMID 39995975, 2025). "s2R/TMEM97 is strongly associated with cell proliferation in cancer and cell proliferation is obviously critical to development." (PMID 38866499, 2024). "In summary, σ2R/TMEM97 is an important protein that has been linked to cancer and a number of neurological disorders." (PMID 36559015, 2022). "It was reported that TMEM97 has been confirmed to be a factor associated with cancer progression, but the related regulatory signalling pathways were not further studied." (PMID 34783163, 2021). "Despite the putative tumor suppressor role of TMEM97 in pancreatic and prostate cancers, this protein is overexpressed in different types of cancer and associated with tumor progression, recurrence and poor survival." (PMID 30574087, 2018). "TMEM97 was recently identified as the Sigma-2 receptor, which plays a key role in mediating Ca2+ and K+ signalling cascades in the endoplasmic reticulum and has been implicated in cancer development and a range of neurological degenerative diseases." (PMID 36834828, 2023). "The data suggest that TMEM97 is associated with cancer proliferation." (PMID 32668577, 2020). "TMEM97 has been implicated in cancer drug resistance in several reports." (PMID 31695608, 2019). "Whereas we started with ARPE19 cells mostly at an epithelial cell state prior to TMEM97 knockdown, the other studies used cancer cell lines, which were possibly at mesenchymal states when TMEM97 siRNAs were applied." (PMID 39995975, 2025). "σ2R/TMEM97 is highly expressed in neurons and cancer cells, and small-molecule allosteric modulators of σ2R/TMEM97 have demonstrated robust neuroprotective effects in various neurological conditions and diseases." (PMID 41008535, 2025). "Second, our finding that TMEM97 suppresses the levels of both E- and N-cadherins is distinct from the findings in cancer research." (PMID 39995975, 2025). "σ2R/TMEM97 is expressed at high levels in the liver, kidneys, and central nervous system (CNS), as well as in cancer cell lines." (PMID 41008535, 2025). "An endoplasmic reticular protein, TMEM97/sigma-2 receptor, involved in cholesterol processing, cell migration, neurodegenerative diseases, and cancer has been shown to be the downstream target (receptor) of histatin-1 (ligand) in epithelial cells." (PMID 40507844, 2025). "The sigma-2 receptor (σ2R/TMEM97) isa clinicallyrelevant membrane protein involved in cholesterol regulation and overexpressedin cancer and neurodegenerative diseases." (PMID 41196005, 2025). "TMEM97, initially known as MAC30, is overexpressed in some cancers and it is believed to be a key player of cholesterol homeostasis and calcium regulation." (PMID 38319380, 2024). "Sigma 2 receptor has been explored as a proliferation biomarker and imaging target for cancer diagnosis for years before transmembrane protein 97 (TMEM97, also known as MAC30) was identified as the bona fide σ2 receptor." (PMID 38067394, 2023). "TMEM97 is a transmembrane protein with a molecular weight of 18-21.5 kDa, which is involved in multiple cancers and cholesterol homeostasis." (PMID 34615853, 2021). "For the first time in the literature, the expression levels of σ1 receptor, PGRMC1, and σ2/TMEM97 were studied simultaneously by Western blot analysis in 23 human cancer cell lines." (PMID 33466391, 2021).